ANGPTL4 (angiopoietin like 4)
Diseases named in the same sentence as ANGPTL4 in open-access papers (continued):
Sharing a sentence is not in itself a finding about the gene and the disease.
tumor (continued). "The data presented is in agreement with studies showing that the expression and roles of ANGPTL4 are context and tumor stage dependent, and that ANGPTL4 has a diverse role in metastasis." (PMID 29100268, 2017). "By using the chick chorio-allantoic membrane (CAM) models, we further showed that inhibition of ANGPTL4 suppressed tumor growth and giant cell formation in vivo." (PMID 28903395, 2017). "The upregulated ANGPTL4 enables tumor cells to disrupt vascular endothelial junctions when arriving the lung capillaries, thereby facilitating their trans-endothelial passage." (PMID 29100268, 2017). "IHC staining revealed that ANGPTL4 expression was elevated in GCT samples as compared with para-tumor normal bone tissues." (PMID 28903395, 2017). "TGF-β signaling is also a significant contributor in the metastatic environment through regulation of chemo-attractants S100A8, S100A9, and ANGPTL4, which enhance tumor cell invasion and disruption of vascular endothelial cell-cell junctions." (PMID 27223426, 2017). "As regards tumor angiogenesis, there are discordant data about the proangiogenic or antiangiogenic role of ANGPTL4." (PMID 28182091, 2017). "The role of ANGPTL4 in lipid metabolism has been well investigated, however, the role of ANGPTL4 in tumor biology remains largely undefined." (PMID 28903395, 2017). "A further investigation is needed using our brain metastasis model to better understand how the tumor microenvironment influences the function of ANGPTL4 in early stages of MBM." (PMID 29100268, 2017). "We propose a mechanism for brain metastasis whereby a soluble factor in the microenvironment of the primary tumor (e.g. TGFβ1) induces the expression of intracellular or extracellular proteins (e.g. ANGPTL4) in cells of the primary tumor." (PMID 29100268, 2017). "ANGPTL4 acts as a tumor suppressor or promoter of cancer metastasis, depending on cell type and stage of cancer." (PMID 29100268, 2017). "One potential link between ANGPTL4 and tumorigenesis is provided by hypoxia conditions, which represent a prominent feature of tumor microenvironment." (PMID 28182091, 2017). "Inhibition of ANGPTL4 expression in UM tumor cells, in turn, reduced the induction by conditioned medium of endothelial cell tubule formation in vitro and the promotion of angiogenesis in vivo." (PMID 26761211, 2016). "Using a tumor array, we demonstrate expression of ANGPTL4 in almost 80% of UM tumors, with expression of either VEGF or ANGPTL4 in 99% of primary UM tumors." (PMID 26761211, 2016). "Inhibition of ANGPTL4 expression by UM tumor cells reduced the induction of endothelial cell tubule formation in vitro and the promotion of angiogenesis in vivo." (PMID 26761211, 2016). "In this regard, we demonstrate that inhibiting expression of both VEGF and ANGPTL4 by UM tumor cells was more effective in preventing secretion of angiogenic factors as compared to inhibiting expression of either angiogenic protein alone." (PMID 26761211, 2016). "To interrogate the role of ANGPTL4 in the regulation of angiogenesis by UM tumor cells, we next knocked down expression of ANGPTL4." (PMID 26761211, 2016). "ANGPTL4 has been reported to have either pro- or anti-angiogenic, as well as either pro- or anti-metastatic effects in different tumor types." (PMID 26761211, 2016). "In neoplastic disease, Angiopoietin-like 4 (ANGPTL4) acts as a negative regulator of apoptosis, regulates angiogenesis and promotes tumour invasion and metastasis." (PMID 26362268, 2015). "In agreement with our results, TGFβ induces ANGPTL4 expression to prime the attachment of tumor cells to microvessels, resulting in metastatic lung colonization." (PMID 25595899, 2015). "Glucose transporter 1 (GLUT1), HK2, ANGPTL4 and VEGF are well known downstream target genes of HIF-1 and are associated with tumor specific metabolic reprogramming, angiogenesis and metastasis." (PMID 25884381, 2015).
tumor (continued). "The Angptl4 gene product is thought to modulate vascular activity and tumor cell motility and invasiveness, which implies its significance for tumor progression and metastasis." (PMID 25853007, 2015). "ANGPTL4 expression is also found in skin, intestines, kidneys, adipose tissues, liver, and a variety of tumours." (PMID 26508818, 2015). "ANGPTL4 has been reported to act not only as a tumor suppressor, but also as an enhancer of tumor metastasis and angiogenesis." (PMID 25955030, 2015). "As shown in 8B, significantly increased binding of STAT3 to the ANGPTL4 promoter was observed in Ad-GSCs as compared to bulk tumor cells." (PMID 25955030, 2015). "Nevertheless, none of these factors showed significant changes from baseline to best tumor response (ANGPTL4, 2.9 to 3.9 ng/mL, p = 0.16; HGF, 0.79 to 0.75 ng/mL, P = 0.60; VEGF-A121, 0.60 to 0.39 ng/mL, P = 0.26)." (PMID 26620439, 2015). "It was also observed that increasing tumour size and increasing degree of hypoxia in the tumour mass promoted the upregulation of ANGPTL4, especially in the hypoxic areas surrounding the necrotic area." (PMID 26508818, 2015). "STAT3 has been shown to activate ANGPTL4 directly or indirectly through transcriptional regulation of VEGF and HIF-1 in various human cancers, so we next examined the relationship of STAT3 and ANGPTL4 expression in GBM to tumor grade and patient survival." (PMID 25955030, 2015). "Studies have shown that ANGPTL4 is a target gene of PPARs, which are involved in the development of tumours." (PMID 26508818, 2015). "The aim of the present review is to address the role of ghrelin, myostatin, leptin, HIF, IL-6, TNF-α, and ANGPTL-4 in the regulation of energy balance, tumour development, and tumoural cell invasion." (PMID 26508818, 2015). "While ANGPTL4 was upregulated by TGF-β in both MDA-MB-231 and M3 cells in vitro, we found that ANGPTL4 was actually downregulated by TGF-β/Smad3 in vivo in the M3 tumors where TGF-β functions as a tumor suppressor." (PMID 24890385, 2014). "Zhu has demonstrated that ANGPTL4 protein is upregulated in tumor tissues of HCC patients compared to normal liver tissue, but only 2 HCC samples were examined on tissue arrays." (PMID 25148701, 2014). "Our study demonstrated several mechanisms of ANGPTL4 in suppressing tumor progression, invasion and metastasis of HCC." (PMID 25148701, 2014). "The result showed that injection of Ad-ANGPTL4 after orthotopic implantation of human liver tumor significantly hindered tumor formation from 3 weeks to 6 weeks." (PMID 25148701, 2014). "The direct effects and mechanisms of ANGPTL4 on regulating tumor microenvironment of HCC are needed further investigation." (PMID 25148701, 2014). "Western blot analysis showed that treatment of Ad-ANGPTL4 suppressed the expression of ROCK1 protein in tumor tissues compared to the control group." (PMID 25148701, 2014). "The result showed that Ad-ANGPTL4 treatment significantly decrease the MVD by 4 folds in tumor compared to control group." (PMID 25148701, 2014). "Consistently, transmission electron microscopy analysis revealed that Ad-ANGPTL4 treatment disrupted the integrity of the tumor endothelial cells and suppressed the invasiveness of the tumor compared to the control group." (PMID 25148701, 2014). "The effect of ANGPTL4 treatment on tumor-microenvironment was therefore studied from different aspects." (PMID 25148701, 2014). "Quantitative RT-PCR was employed to study the expression levels of ANGPTL4 mRNA in paired tumor and non-tumor liver tissues from 110 HCC patients and in liver tissues from 26 healthy donors." (PMID 25148701, 2014). "The average tumor volume at week 6 was reduced by 11.6 folds after Ad-ANGPTL4 treatment compared to the control group." (PMID 25148701, 2014). "On the other hand, ANGPTL4 is an anti-metastatic protein on tumor cells through inhibition of vascular permeability, motility and invasiveness." (PMID 25148701, 2014).
tumor (continued). "The relative ANGPTL4 CNV value in tumor tissues of HCC patients was determined to be significantly lower than in non-tumor tissues (p = 0.025, unpaired two-tailed t-test)." (PMID 25148701, 2014). "Overexpression of ANGPTL4 can promote tumorigenesis, tumor invasion, angiogenesis, anoikis resistance and metastasis." (PMID 25148701, 2014). "Of relevance, a recent study has reported that expression of ANGPTL4 correlates with the depth of tumour invasion, venous invasion and Duke’s classification in CRC." (PMID 24180698, 2013). "Tumor sections were prepared for examination of the microvessel density; the microvessel density was significantly decreased in tumor xenografts of the Angptl4-knockdown cells." (PMID 23617883, 2013). "Over the last few years, a number of experimental studies have further demonstrated that Angptl4 is involved in key events of tumor growth." (PMID 23783408, 2013). "Similar mechanisms have been reported for ANGPTL4, which supports tumor progression through metastasis and vasculogenesis." (PMID 23969837, 2013). "Angiopoietin-like protein 4 (ANGPTL4) has been reported to promote tumor growth, metastasis, and angiogenesis under certain conditions." (PMID 23925665, 2013). "Although ANGPTL4 was reported to increase or decrease tumor growth and angiogenesis depending on the cancer types, it did not seem to be a major player in this model as its efficient suppression did not alter how fast the tumors grew." (PMID 24260413, 2013). "Among the 60 angiogenic factors, we first found that Angptl4 expression was significantly induced by EGFRvIII overexpression, and that Angptl4 acts as a pro-angiogenic factor in tumor xenografts." (PMID 23617883, 2013). "Recent biochemical and genetic studies in mouse and humans have identified Angptl4 as a critical hormonal regulator of TG-rich lipoprotein metabolism, angiogenesis, and tumor cell survival and metastasis." (PMID 22479192, 2012). "Together these studies implicate tumor-derived ANGPTL4 in cancer metastasis via its effect on endothelial integrity and cellular migration." (PMID 22481923, 2012). "ANGPTL4 expression is widespread among various tumors, and its suppression impairs tumor growth due to the enhanced apoptosis." (PMID 22481923, 2012). "Recently identified as a tumor-secreted pro-metastasis factor and as a matricellular protein, ANGPTL4 is upregulated in many epithelial tumors." (PMID 22481923, 2012). "ANGPTL4 was recently defined as a matricellular protein with a potential role in tumor growth; however, the role of ANGPTL4 in metastasis still remains contradictory." (PMID 22481923, 2012). "Its role in vascular and tumor processes is more debated, and suggestive of a context, tissue specific activity of ANGPTL4." (PMID 20454689, 2010). "ANGPTL4 can inhibit tumor cells (B16F0) motility and invasiveness and exhibit anti-angiogenic properties." (PMID 19287498, 2009). "Additionally, PIK3CA mutations enrich for MMP9+ macrophages that promote tumor angiogenesis through ANGPTL4 signaling." (PMID 41958669, 2026). "ANGPTL4 expression in tumor tissues was determined via immunohistochemistry." (PMID 42028751, 2026). "Together these results suggest that ANGPTL4 SASP factor promotes tumor initiation." (PMID 41347893, 2026). "In the senescent cell microenvironment, ANGPTL4 could thus contribute to senescence‐dependent alterations such as inflammation and tumor initiation." (PMID 41347893, 2026). "Furthermore, ANGPTL4 expression in tumor cells is essential for adipocyte-driven glycolysis and metastasis." (PMID 40616161, 2025). "Furthermore, ANGPTL4 inhibition via antisense oligonucleotides or c-ANGPTL4 antibodies lead to dose-dependent attenuation of EMT markers in a 3D-tumor model." (PMID 40233044, 2025). "Additionally, ANGPTL4 was found to promote macrophage M2 polarization within the tumor microenvironment via paracrine signaling, further driving TNBC progression." (PMID 39910592, 2025).
tumor (continued). "Although ANGPTL4 expression does not correlate with overall survival, it is significantly associated with tumor invasion, indicating a potential role in metastasis." (PMID 40723247, 2025). "Interestingly, ANGPTL4 has been shown to exhibit both pro-tumor—promoting tumor growth, cell survival, angiogenesis and metastasis—as well as anti-tumor activities, underscoring its complex roles in cancer biology." (PMID 40723247, 2025). "This indicates that the role of ANGPTL4 in ccRCC is complex and nANGPTL4 may act as a tumor suppressor in a subset of samples, while cANGPTL4 can promote tumor progression." (PMID 40723247, 2025). "There are studies that emphasize the role of ANGPTL4 in tumor angiogenesis." (PMID 40076810, 2025). "Numerous studies have shown that ANGPTL4 is involved in tumor metastasis and angiogenesis." (PMID 41425595, 2025). "Previous studies have suggested that ANGPTL4 has great potential as a molecular marker in tumor diagnosis and patient prognosis, as it regulates tumor progression through various signaling pathways, including Extracellular signal-related kinases 1 and 2 (ERK1/2)." (PMID 38311733, 2024). "As ANGPTL4 is known to regulate lipid metabolism, these data strongly suggest that ANGPTL4 may suppress ccRCC tumor progression via regulating lipid metabolism." (PMID 39105498, 2024). "Collectively, the elevated expression of CD36 and ANGPTL4 in overweight/obese TNBC patients may suggest more extensive metabolic reprogramming of cancer cells in response to the obese adipose tissue tumor microenvironment." (PMID 39456610, 2024). "ANGPTL4 is highly expressed in various cancers, including colorectal, prostate, breast, and liver cancers, where it plays roles in regulating tumor growth, angiogenesis, redox balance, tumor invasion, and metastasis." (PMID 39840089, 2024). "As these results may suggest a tumor-promoting function for ANGPTL4, we next looked at the colony formation ability under different conditions." (PMID 39105498, 2024). "Recent studies have indicated that ANGPTL4 plays a contradictory role in tumor angiogenesis." (PMID 38212795, 2024). "In OC, it has been shown that ANGPTL4 reduces angiogenesis, thereby inhibiting tumor growth." (PMID 38311733, 2024). "The interaction of ANGPTL4 with different proteins in the tumor microenvironment may be one of the reasons for its paradoxical effect on angiogenesis in different diseases or cell lines." (PMID 38212795, 2024). "Using RCC tumor models with WT VHL, we demonstrate that ANGPTL4 behaves as a tumor suppressor." (PMID 39105498, 2024). "Therefore, we further examined the role of the ESM1/ANGPTL4 interaction on the molecular biological behavior of endothelial cells in the OC tumor microenvironment." (PMID 38212795, 2024). "CD36, FABP4, and ANGPTL4 were readily detectable in tumor cells by immunostaining." (PMID 39456610, 2024). "Hypoxia-driven ANGPTL4 expression facilitates tumor growth and metastasis, and may thus serve as both a molecular marker for the diagnosis of OC and a target for drug discovery." (PMID 38311733, 2024). "Conversely, ANGPTL4 inhibition significantly repressed the tumor weight and volume of SKOV3 cells with low vimentin, PCNA, MMP9, ESM1 and CD34 expression in comparison with the vector and NC groups, which could also be rescued by Colivelin." (PMID 38212795, 2024). "ANGPTL4 overexpression could promote OC cell growth (tumor weight and volume) with higher expression of vimentin, proliferating cell nuclear antigen (PCNA), MMP9, ESM1 and CD34, which could be rescued by AG490." (PMID 38212795, 2024). "These disagreements indicated that the effect of ANGPTL4 may be highly dependent on the molecular interactions in the tumor microenvironment of different tumor types and is closely related to the subcellular localization of its executive function." (PMID 38212795, 2024).
tumor (continued). "On the one hand, tumor cells may act on PCs by secreting oncogenic molecules (ANGPTL4 or LAMB3) to inhibit their antitumor function or promote isotype switching of protumor subtypes." (PMID 37138324, 2023). "Cancer-associated mesothelial cells secrete ANGPTL4 and STC1, which directly drive OvCa, endothelial, and monocyte cell function in the tumor microenvironment, and targeting ANGPTL4 and STC1 interferes with the tumor-promoting capabilities of cancer-associated mesothelial cells." (PMID 36795484, 2023). "In addition to its impact on tumor-induced angiogenesis, we found that EC-specific deletion of Angptl4 decreased tumor-mediated vascular permeability." (PMID 38086791, 2023). "First, we analyzed the expression of IL-8 and ANGPTL4 in the tumor tissues of CRC patients." (PMID 37649607, 2023). "We speculate that hypoxic tumor cells may secrete ANGPTL4 to communicate with SDC1+ PCs, affecting their differentiation, survival, and/or antibody secretion." (PMID 37138324, 2023). "However, more studies are needed to determine if ANGPTL4 and/or STC1 are the major drivers of tumor-promoting functions of cancer-associated mesothelial cells, and if these proteins play a key role in the chemoresistance and immunotherapy resistance of OvCa." (PMID 36795484, 2023). "It has been shown that tumor-derived ANGPTL4 could suppress in vitro vascular tube formation and proliferation of human umbilical vascular endothelial cells, partly due to suppression of ERK signaling." (PMID 37217704, 2023). "Moreover, ANGPTL4 can participate in tumor energy metabolism in different NSCLC cells and affect cell proliferation through this process." (PMID 36447119, 2023). "Moreover, the up-regulation of PPAR β/δ was associated with the increased expression of both ANGPTL4, a PPAR β/δ target gene involved in angiogenesis and tumor development, and the extracellular matrix proteins elastin, collagen 3α, and fibronectin." (PMID 37048084, 2023). "In contrast, ANGPTL4 is more important in tumor energy metabolism, antioxidant and metastasis." (PMID 36447119, 2023). "The binding of ANGPTL4 to endothelial cells disrupted their connectivity, increased permeability of pulmonary capillaries, and promoted transvascular endothelial migration of tumor cells." (PMID 37091977, 2023). "In this study, we identified that hypoxia-like tumor cells may also act on SDC1/CD138+ IgG1 PCs by secreting ANGPTL4." (PMID 37138324, 2023). "Moreover, the immunohistochemistry assay confirmed that ANGPTL4 possessed a higher average optical density (AOD) in A549-ANGPTL4-OE xenograft tumour compared to its NC group, and irradiation reduced the AOD level of Ki67 i.e. inhibited cell proliferation." (PMID 36050447, 2022). "Given that ANGPTL4 has emerged as a crucial player in cancer progression, it is important to know whether ANGPTL4 undergoes the regulation of tumour radioresistance under hypoxia and how its contribution in the signalling communication within TME." (PMID 36050447, 2022). "Additionally, upregulation of Angptl4 enhanced tumor growth in a xenograft model of PDAC (Panc-1) cells." (PMID 36074318, 2022). "The function of ANGPTL4 in tumor tissues is still under debate." (PMID 35692877, 2022). "ANGPTL4 has been found to play an important role in the process of tumour metastasis." (PMID 35810469, 2022). "Indeed, ANGPTL4 was found to prevent lung carcinoma and melanoma metastases via the inhibition of vascular permeability, tumor cell motility, and invasiveness." (PMID 36074318, 2022). "Since HIF-1α is the gold standard for identifying hypoxia, this result suggests that ANGPTL4 may also be a conspicuous molecule distinguishing hypoxic tumour cells from normoxic cells." (PMID 36050447, 2022).